MIR4675 (microRNA 4675)
Synonyms: hsa-mir-4675
Gene: MicroRNA gene on chromosome 10 (20,551,970 to 20,552,046, forward strand). Ensembl gene ENSG00000265372.
Diseases named in the same sentence as MIR4675 in open-access papers:
MIR4675 is named in the same sentence as 2 diseases in open-access papers, as found by Europe PMC text mining. Sharing a sentence is not in itself a finding about the gene and the disease. The quoted sentences say what the papers report.
lung carcinoma (1 paper, 2021). "Further works are warranted to establish the role of MIR4675 and CNVR2239.1 in lung cancer." (PMID 34178039, 2021).
MIR4675 also shares sentences with these, for which no sentence is quoted: cancer (1 paper).